MTOR (mechanistic target of rapamycin kinase)
Diseases named in the same sentence as MTOR in open-access papers (continued):
Sharing a sentence is not in itself a finding about the gene and the disease.
tumor (continued). "mTOR signaling protein abundance was significantly reduced in tumor lysates from GLE-treated mice, where mTOR, p70S6K and eIF4G expression was reduced." (PMID 28758107, 2017). "The PTEN phosphatase is a tumor suppressor that is critical for genome stability and a negative regulator of the mTOR kinase pathway." (PMID 28640831, 2017). "Such inhibitory effect on tumor growth is reversed by application of IGF1 ((IGF1R ligand) or MHY1485 (mTOR agonist) in vitro." (PMID 28624790, 2017). "The deregulation of the mammalian target of rapamycin (mTOR) and other proteins of this pathway occurs in many solid tumors and tumor cells have more sensitivity to mTOR inhibitors than normal cells." (PMID 28286604, 2017). "Rapamycin inhibits the mammalian target of rapamycin (mTOR), a serine/threonine kinase often upregulated in malignant cells and played a key role in tumor development and progression." (PMID 28186966, 2017). "Taken together, the results and the data showed that COFL1 and PROF1 expression in HCT‐116 and DLD‐1 cells is essential to implication in oxidative stress and PI3K/mTOR/p70S6K, signalling that erinacine A inhibited cell invasion and tumour growth." (PMID 27709782, 2017). "Further molecular targets of tumor cell growth cascades include the mammalian target of rapamycin (mTOR) pathway." (PMID 28796163, 2017). "The significance and function of the AKT-independent activation of the mTOR complexes in the context of tumor dormancy remain to be elucidated, but it exemplifies the complex molecular interactions often observed in the study of tumor dormancy." (PMID 29263786, 2017). "miR-17-5p belongs to the miR-17-92 cluster, which is involved in tumor proliferation by controlling the PI3K/Akt/mTOR pathway." (PMID 29050253, 2017). "Studies investigating the PI3K inhibitor XL146, the AKT inhibitor GSK690693 and the mTOR inhibitor MLN0128 all demonstrated modest anti-tumor activity in preclinical models." (PMID 27926496, 2017). "In our study, HCaRG overexpression significantly reduced tumor vascularization most probably by suppressing VEGF through the inactivation of AKT/mTOR/HIF signaling independently of abnormal VHL expression." (PMID 29050225, 2017). "Perhaps more often, targeted agents promote the activation of adaptive survival signaling in tumor cells, either by the same or parallel pathways to mTOR." (PMID 28822012, 2017). "In colonic and pancreatic ACs, p-mTOR staining was diffuse in overall tumor cell population but intensified at the invasive front of the tumor." (PMID 28831205, 2017). "mTOR is assumed to play a critical role in tumor vascularization, as it is part of the phosphatidylinositol 3-kinase/Akt/mTOR signalling pathway, which is implicated in tumor angiogenesis." (PMID 29232371, 2017). "It was initially recognized as a tumor suppressor due to its function in inhibiting the mTOR pathway and tumor cell proliferation." (PMID 27911269, 2017). "Previous studies in TSC patients indicated that blood levels of tumor vascularization mediators are reduced in response to mTOR inhibitor therapy reflecting the strong effect on AML vascularization." (PMID 29232371, 2017). "This inhibitor targets mTOR signaling in several relevant tumor models at an oral dose of 5 mg/kg in tumor-bearing mice." (PMID 28362357, 2017). "To further elucidate the role of the Akt/mTOR pathway in ibrutinib-induced autophagy, we evaluated the expression of LC3A/B, p-Akt, and p-mTOR in the mice tumor by western blotting." (PMID 28716053, 2017). "We prove that challenging conditions by serum deprivation force self‐sustaining tumor cells to switch from AKT/mTOR to a RSK/mTOR signaling cascade." (PMID 28675785, 2017). "Rap is an anti-tumor IS drug that is known to suppress T and B cell proliferation via mTOR inhibition." (PMID 28345001, 2017). "Overactivation of AKT/mTOR signaling pathway plays a prominent role in tumor initiation, progression, and prognosis." (PMID 28212545, 2017).
tumor (continued). "The failures in PI3K/Akt/mTOR signalling pathway and hyperactivated mTOR kinase have been described in many tumours." (PMID 28578659, 2017). "Euglenophycin-treated HCT116 and HT29 tumor xenografts demonstrated reduced mTOR and elevated LC3B protein expression." (PMID 29262645, 2017). "Also, the changes in the morphology of the cells may also be mediated by other mechanisms, such as suppression of the Akt/mTOR pathway and induction of autophagy, since both pathways have been implicated in the inhibitory activity of α-solanine towards tumor cells." (PMID 29201465, 2017). "In summary, Rab7 GTPase plays a key role in regulating MDSCs development, differentiation, trans-endothelial migration, anti-tumor immunity and direct tumor stimulation through physical interaction with the mTOR complexes." (PMID 28415797, 2017). "Generally speaking, TSC2 exerts its tumor suppressor function through negative regulation mTOR pathways which negatively regulate autophagy." (PMID 28387735, 2017). "Our recent results highlight the additional role of mTOR as a tumor suppressor, explaining these modest results in the clinic." (PMID 28616576, 2017). "The FAK/PI3K/AKT/mTOR signaling pathway plays important roles in cell proliferation, differentiation, survival and tumor cell metastasis." (PMID 29280977, 2017). "We show that CRNDE knockdown inhibits tumor angiogenesis and tumor growth via activating mammalian target of rapamycin (mTOR) signaling." (PMID 28178668, 2017). "Phospho-S6 immunolabeling indicated that mTOR signaling is activated in multiple cell populations in wild-type retina and in the dysplastic retina and advanced tumor." (PMID 28192065, 2017). "Blockade of the PI3K/Akt/mTOR signalling axis was shown to attenuate the Heat Shock Factor (HSF1)-driven cellular heat shock stress response (HSR) in tumor cells." (PMID 28794469, 2017). "Some tumor types have shown response when treated with mTOR inhibitors (temsirolimus, everolimus, and ridaforolimus) and this class of drugs has also been assessed in OC." (PMID 28286604, 2017). "Decreased phosphor-mTOR (Ser2448) expression was observed in GSK-470 treated tumor sample, whereas PP242 inhibited phosphorylation of mTOR at both Ser2448 and Ser2481." (PMID 28402933, 2017). "We are the first group showing that MDSCs directly stimulate proliferation of various tumor cells in vitro, tumor growth in vivo and metastatic invasion, which are mediated by over-activation of mTOR." (PMID 28415797, 2017). "p-mTOR showed membranous and/or cytoplasmic staining in the tumor cells with variable intensity depending on the tumor phenotype." (PMID 28831205, 2017). "The PI3K/AKT/mTOR signaling pathway is a critical effector for cell proliferation and tumor progression." (PMID 29262623, 2017). "Rapamycin, an mTOR inhibitor, hinders cell proliferation along with sphere formation in vitro and impedes tumor growth in vivo." (PMID 28903328, 2017). "According to our results and the known microenvironmental tumour promoting effects of tumour derived lactate, not only the well-known anti-proliferative effect of mTOR inhibitors should be considered." (PMID 28578659, 2017). "Collectively, these data show that 111In-bevacizumab is a specific radiotracer to visualise VEGF within tumours and monitor response to anti-angiogenic therapy mediated by mTOR inhibition." (PMID 28560583, 2017). "Since then, numerous pre-clinical studies have confirmed that blocking mTOR impairs tumor progression." (PMID 29104248, 2017). "Collectively our data argue that inactivation of mTOR and the induction of autophagic flux play a major role in the anti-tumor activity of neratinib and the [neratinib + valproate] drug combination." (PMID 29163826, 2017). "Last but not least, CD147 can down-regulate Beclin 1 and inhibit starvation-induced autophagy through the PI3K/Akt/mTOR pathway, modulating the apoptosis of tumor." (PMID 28881651, 2017).
tumor (continued). "Several studies have shown that FAK/PI3K/AKT/mTOR signaling is involved in cell proliferation, differentiation, survival and tumor metastasis, and the signaling pathway is also involved in the regulation of MMP-2 and MMP-9." (PMID 29280977, 2017). "An increasing number of studies have demonstrated that the Akt-mTOR pathway controls autophagy induction, and anticancer agents can inhibit tumor survival and growth via suppression of the Akt-mTOR pathway along with stimulation of autophagy." (PMID 28891980, 2017). "Several genomic regions were preferentially amplified or deleted in tumours harbouring IDC, including gain of BCL6 and loss of MTOR, along with gains of a region harbouring CDK2 and ERBB3." (PMID 28067867, 2017). "Numerous studies have reported that Mcl-1 protein levels are inhibited by targeting PI3K/Akt and/or mTOR pathways using specific inhibitors, leading to increased tumor cell killing in both in vitro and in vivo models." (PMID 29228561, 2017). "Tumor vessel normalization by anti-angiogenic drugs was initially observed with bevacizumab and further investigated for mTOR inhibitors." (PMID 29104248, 2017). "While mTOR activation programs their differentiation into functionally distinct lineages, mTOR inhibition drives T cell toward long-lived tumor specific memory T cells." (PMID 28822012, 2017). "Inhibitors of the VEGF and mTOR signaling pathways can reduce angiogenesis, tumor growth, and proliferation and thereby increase PFS as well as OS in mRCC." (PMID 28796163, 2017). "Taken together, our findings suggest a model in which miR-363-3p regulates both the mTOR/Cyclin D1 pathway and the Erk-cyclin D1 pathway to inhibit tumor cell growth." (PMID 28423618, 2017). "We assessed the respective anti-tumor activity of the following PI3K/AKT/mTOR pathway inhibitors: BEZ235 (dual inhibitor of PI3K, mTORC1 and mTORC2), BKM120 (PI3K inhibitor) and everolimus (mTORC1 inhibitor)." (PMID 28002802, 2017). "For example, TGF-β can increase VEGF expression via Src/Fak/Akt signaling to promote angiogenesis, and activate HIFs through PI3K/Akt/mTOR signaling to regulate metabolism and growth of tumor cells." (PMID 28417919, 2017). "In tumor models of metastatic pancreatic and hepatocellular carcinoma, the combination of selumetinib with the mTOR inhibitor rapamycin enhanced anti-tumor activity compared with either agent alone." (PMID 28424891, 2017). "Preclinical models have showed that inhibition of the PI3K/mTOR pathway decreases tumour activity and induced apoptosis when combined with oestrogen deprivation in ER+ tumour cells, providing a rationale for combining the two regimens in a clinical setting." (PMID 27923036, 2017). "AKT/mTOR pathways were known to play an important role in the proliferation, survival, and motility of tumor cells." (PMID 28280729, 2017). "In the present study, we show that everolimus and metformin both inhibit mTOR activity and have additive inhibitory effects on glucose metabolism, tumor cell growth and colony formation." (PMID 28356082, 2017). "For instance, compensatory increased Akt and/or ERK signaling after mTOR inhibition are responsible for tumor relapse and their targeted agents have been widely investigated." (PMID 28822012, 2017). "For example, mutations in EGFR and MLL2 were private to 327_T_PDO, whereas tumour 278_T and its models diverged for mutations in FAM123B, MTOR, and for a PTCH1 frameshift mutation predicted to activate oncogenic sonic hedgehog signalling." (PMID 28186126, 2017). "As Ras/MAPK and AKT/mTOR signaling cascades are critical pathways for tumor cell growth, MEK and AKT inhibitors have been developed." (PMID 28877210, 2017). "Previous study has indicated that 36% of SCLC patients’ tumor samples harbor genetic alterations in PI3K/AKT/mTOR pathway." (PMID 29290965, 2017).
tumor (continued). "The BET-bromodomain inhibitor OTX015 (MK-8628) has potent antiproliferative activity accompanied by c-MYC down-regulation in several tumor types, and has demonstrated synergism with the mTOR inhibitor everolimus in different models." (PMID 27935867, 2017). "Surface expressed PD-L1 is important for Akt/mTOR signaling to promote mTOR activity and glycolytic metabolism in tumor cells." (PMID 28348562, 2017). "PML also regulates cell growth, stress responses and tumor suppression through a complex relationship with the mechanistic target of rapamycin (mTOR)." (PMID 28332630, 2017). "The gene responsible for BHD syndrome, the folliculin (FLCN) gene on chromosome 17p11.2, is a tumor suppressor gene that was first reported in 2002 and is known to be involved in the signaling of mammalian target of rapamycin (mTOR)." (PMID 28558743, 2017). "A recent study showed that co-targeting mTOR and PD-L1 enhances tumor control by increasing the IFNγ production capacity in peripheral and tumor-infiltrating CD8 T cells in a syngeneic oral cavity cancer model." (PMID 28822012, 2017). "The results also suggested that lenti-UCA1-siRNA stably-transfected BGC-823 cells significantly inhibited p-AKT3 and p-mTOR protein expression in isolated tumor tissues of these animals." (PMID 29212166, 2017). "Additional finding in HCC was that p-mTOR staining was intensified in the periphery of the primary tumor." (PMID 28831205, 2017). "Recent studies identified a potential signaling pathway named PI3K/AKT/mTOR, which plays an important role in survival, growth, proliferation, transformation, metabolism, and angiogenesis of tumor cells." (PMID 28114374, 2017). "The mammalian target of rapamycin (mTOR) play a key role in the regulation of tumor cell proliferation and survival." (PMID 28811537, 2017). "Aberrantly activated RTKs have been reported to promote NB tumor progression through activating signaling pathways such as PI3K/AKT/mTOR and JAK/STAT3." (PMID 27564113, 2017). "mTOR activity is markedly increased in tumour cells and mTOR is highly phosphorylated in these cells." (PMID 29179444, 2017). "In this study, we first reported that BMX can promote cell proliferation and tumor progression through the PI3K/AKT/mTOR and STAT3 pathways." (PMID 28514765, 2017). "Multikinase and mTOR inhibitors of signaling pathways of neoangiogenesis and tumor growth significantly and effectively improve PFS and OS in mRCC." (PMID 28796163, 2017). "In this study, we systematically estimate PI3K-Akt-mTOR pathway activity in breast primary tumor samples using transcriptomic profiles derived from drug treatment in MCF7 cell lines." (PMID 27589846, 2016). "The findings suggest that the expression of mTOR at the protein level was significantly lower than in the corresponding normal gastric mucosa, while the ratio of p-mTOR was significantly increased in tumor tissues." (PMID 28005970, 2016). "Mice with a myeloid-specific deletion of mTOR have poor M-MDSCs after grafting with allo-skin tissue or a tumor." (PMID 26833095, 2016). "Vps34, a member of the phosphatidylinositol 3-/4 (PI3/PI4)-kinase family, plays an important role in the regulation of mTOR protein synthesis, and also forms a complex with beclin-1 that promotes autophagy and tumor suppression." (PMID 27070592, 2016). "The neoplasm was so big and close to the hepatic vein, but it showed obvious shrinkage after upfront treatment with mTOR inhibitor sirolimus for 8 months." (PMID 28002331, 2016). "Given the modest responses to everolimus, a mTOR inhibitor, in multiple tumor types, there is a pressing need to identify predictive biomarkers for this drug." (PMID 26859683, 2016). "In contrast to pERK, immunostaining to detect phosphorylated ribosomal protein S6 (pS6), an indicator of mTOR signaling, was detected broadly throughout the tumor masses." (PMID 26859571, 2016).
tumor (continued). "Over-expression of chaperones maintained AKT/mTOR activity in the presence of drugs and protected tumor cells from the drug combination." (PMID 27379204, 2016). "Herein, PI3K/AKT/MTOR inhibitors induce autophagic tumor properties, whereas RAF/MEK/ERK signalling inhibitors reduce expression of autophagic markers." (PMID 26802026, 2016). "Inhibition of mTOR activity by everolimus was effective in altering tumor metabolism with a profound effect on glycolysis, polyamines, dipeptides, glycerophosphodiesters, and nucleotides in both obese and lean KpB mice." (PMID 26959121, 2016). "The ATP-competitive inhibitor Torin-2 is a second-generation drug directed against mTOR, which represents an encouraging therapeutic target in several human neoplasms, also for dual targeting treatment." (PMID 27821800, 2016). "Expression of activated MEK1 was not protective, however activated MEK1 enhanced the ability of activated mTOR to protect the tumor cells." (PMID 27259258, 2016). "In order to investigate the mechanism underlying the inhibition of tumor growth by Sal B in vivo, we detected the expression of LC3B, p-AKT and p-mTOR by western blotting." (PMID 27557491, 2016). "For example, molecular markers such as mTOR and Src are reportedly involved in the development of ER– tumor metastasis." (PMID 27147578, 2016). "Although rapamycin dose for tumor treatment is a little lower than that used for immunosuppression in transplantation, mTOR inhibitors still have the potential in immunosuppression." (PMID 27274989, 2016). "Since mTOR is expressed in tumor tissues and healthy organs, the sensitivity or resistance to mTOR inhibitors cannot be predicted upon the presence of the target." (PMID 27374081, 2016). "The fixed 10-mg dosing regimen of everolimus is based on its safety profile together with its pharmacodynamic effects on the mTOR-dependent pathway in tumor and skin biopsies." (PMID 27169792, 2016). "Both LY2835219 and mTOR inhibitor suppressed tumor growth of HNSCC as single agent, and the combination of these two agents resulted in synergistic tumor growth inhibition." (PMID 26909611, 2016). "Animal models have demonstrated that agents targeting the mTOR pathway can lead to significant inhibition of proliferation, differentiation, and tumor progression in specific PDAC subpopulations." (PMID 27200288, 2016). "Taken together, our data suggest that Sal B inhibited tumor growth in vivo by inducing autophagy through suppressing AKT/mTOR pathway." (PMID 27557491, 2016). "In tumour cells, the phosphoinositide 3-kinase (PI3K)–Akt–mammalian target of rapamycin (mTOR) pathway is always turned on due to mutation of key genes in this pathway." (PMID 27388367, 2016). "The HPV-16 E6 and E7 oncoproteins activate the PI3K/Akt/mTOR signaling pathway to affect tumor initiation and progression." (PMID 27231932, 2016). "The patients are receiving immunosuppressive therapy to reduce graft rejection, but differential side effects have been related to calcineurin and mTOR inhibitor administration regarding tumor recurrence and nephrotoxicity." (PMID 27518575, 2016). "This is particularly interesting as PD-L1 has been identified to play a pivotal role in licensing glycolytic metabolism of tumor cells via AKT/mTOR, which limits nutrients needed for T cell survival and function." (PMID 27705910, 2016). "NVP-BEZ235 is a promising PI3K/mTOR dual inhibitor exhibiting improved anti-tumor potential compared to rapamycin analogs." (PMID 26967052, 2016). "For further analysis, patients were separated into two groups, low and high p-mTOR, based on the median percentage (40%) of positive tumor cells." (PMID 27096957, 2016). "Dual suppression of mTOR and glycolysis synergistically blunts the proliferation and tumor development of mTOR hyperactive cells." (PMID 26918353, 2016).